MTOR (mechanistic target of rapamycin kinase)
Diseases named in the same sentence as MTOR in open-access papers (continued):
Sharing a sentence is not in itself a finding about the gene and the disease.
depression (continued). "Considering the contrasting functions of PI3K/Akt/mTOR in depression and aging, it will be interesting to conduct further experimental investigations to elucidate their exact roles and functions in the development of NPDs and accelerated aging." (PMID 38926475, 2024). "The expression of mTOR in depression was controversial and includes increases, decreases and no significant changes." (PMID 37308476, 2023). "The mammalian target of rapamycin (mTOR), as a downstream cascade of BDNF, had been implicated in protein synthesis-dependent synaptic plasticity and can be interrupted in depression." (PMID 37308476, 2023). "Mfn2 mediated the anti-depressive role of MOOs with the PI3K/Akt/mTOR pathway during hypertension with depression." (PMID 36765376, 2023). "We found MOOs upregulated Mfn2 expression to activate the PI3K/Akt/mTOR pathway-mediated mitophagy, which removing impaired mitochondria in astrocytes during hypertension with depression." (PMID 36765376, 2023). "Of note, some studies also reported a critical role of Akt dysregulation in depression and anxiety, possibly mediated by the mTOR (mammalian target of rapamycin) cascade and the disruption of neurogenesis." (PMID 36768626, 2023). "AMP-activated protein kinase (AMPK) has been shown to regulate the activity of several kinases, including pAKT, p38MAPK, and mTOR, which are important signaling pathways in the treatment of depression." (PMID 36979839, 2023). "Moigneu, Abdellaoui and colleagues show that GDF11 attenuates depression-like behavior and improves memory in aged mice through neuronal autophagy and mTOR." (PMID 37118117, 2023). "Given that the PI3K/AKT/mTOR pathway plays a role in the pathophysiology of depression, it is conceivable that artesunate suppresses depressive‐like symptoms by suppressing this pathway." (PMID 36573693, 2023). "Our results show that mTOR and GSK3β signaling was profoundly altered in the chronic depression model used in this study, and that fluoxetine reversed in part these alterations in normal mice but not in OCT2 mutants." (PMID 37775532, 2023). "Dysfunction of mTOR is involved in the etiology of different neuropsychiatric disorders, including depression." (PMID 36979839, 2023). "In addition to this, the administration of subanesthetic ketamine in three patients with depression caused an abrupt decrease in the depressive symptoms which may be associated with an acute increase in the plasma mTOR, GSK-3 expression, and phosphorylation of the eEF2." (PMID 36045116, 2022). "Subsequently, various studies confirmed the crucial role of mTOR in the treatment and pathophysiology of depression." (PMID 34983570, 2022). "SGKL treatment improves the depression‐induced alteration of gut microbiota that stimulates the phosphorylation of the PI3K/Akt/mTOR pathway, which represses microglial activation through PI3K/Akt/mTOR pathway‐regulated inflammation in the hippocampus." (PMID 35713215, 2022). "Collectively, the results indicated that the PI3K/Akt/mTOR pathway is the target of SGKL treatment that mediates the improvement of depression‐like behavior and inflammation in CRS rats." (PMID 35713215, 2022). "Akt-mTOR signalling, one of the pathway phenotypes involved in the function of synapses by activating protein synthesis and alleviating depression or anxiety, is also enhanced upon HDAC3 inhibition." (PMID 35251047, 2022). "An increase in phosphorylated mTOR and improved cognitive performance have been observed in the pharmaco-resistant model of depression following iTBS." (PMID 35656538, 2022). "For example, mTOR signaling has been extensively investigated in the pathogenesis and treatment of depression." (PMID 35465614, 2022). "Several studies have found that decreasing mTOR activation in animal depression models is beneficial." (PMID 35610650, 2022). "Several investigations have reported decreased brain mTOR activation in animal models of depression." (PMID 35782423, 2022).
depression (continued). "Generally, differential metabolites were associated with depression‐like behaviors, inflammation, and PI3K/Akt/mTOR pathway." (PMID 35713215, 2022). "In fact, when a model of resistant depression was utilized, mTOR levels were significantly reduced in the prefrontal cortex, despite a behavioral antidepressant response." (PMID 35546951, 2022). "Akt-mTOR signalling is a pathway phenotype involved in the function of synapses that activates protein synthesis, alleviating depression or anxiety." (PMID 35251047, 2022). "According to Spearman correlation, the correlation between PI3K/Akt/mTOR pathway and gut microbiota or metabolites can explain how SGKL treatment affects the PI3K/Akt/mTOR pathway activity in the hippocampus during depression progression." (PMID 35713215, 2022). "Yueju pill exerted antidepressant effects by regulating PKA/CREB, NMDA, and Akt/mTOR signaling, while Chaihu Shugan San has been suggested to treat depression through BDNF signaling, gut microbiota, and other mechanisms." (PMID 34976096, 2021). "In this study, KEGG results revealed that the up-regulation of leucine after ACE treatment regulated the mTOR signaling pathway in depression mice." (PMID 34413798, 2021). "There is a high comorbidity between neurodegenerative disorders, in which mTOR inhibitors are used as therapeutic approaches, cognitive defects and emotional dysregulation, such as anxiety and depression." (PMID 33723223, 2021). "Our data are in accordance with previous findings on the importance of the mTOR pathway in major depression." (PMID 34445375, 2021). "Jiaotai Wan regulates PI3K/AKT/mTOR signaling pathway related proteins to improve depression and reverse behavioral changes in rats." (PMID 34659436, 2021). "Overall, these neurochemical results suggest that SY upregulates the expression of BDNF/TrkB and the PI3K/Akt/mTOR signaling pathway to ameliorate CUMS-induced depression-like symptoms in rats." (PMID 33584387, 2021). "In contrast, inhibition of mTor by rapamycin reverses the antidepressant effects of ketamine in patients with depression." (PMID 33514378, 2021). "Our results demonstrated essential roles of PTEN, negative regulator of AKT/mTOR signaling, in regulating depression-like behaviors as well as CRS- and Dex-induced neuronal atrophy in mice." (PMID 33771972, 2021). "Lower expression AMPAR, impaired mTOR complex signaling pathway, and lower level of brain-derived neurotrophic factor (BDNF) is linked to neuronal atrophy and depression." (PMID 33679340, 2021). "We further evaluated the expression of PI3K/Akt/mTOR-mediated BDNF/TrkB pathway-related proteins to investigate the role of SY in depression." (PMID 33584387, 2021). "MAPK1 as one of the important regulated gene in the mTOR signaling pathway which plays an important role in synaptic plasticity in Alzheimer’s disease and relate to the depression disorder as well as functioning of the immune system." (PMID 34848731, 2021). "In particular, the major components of the PI3K/Akt pathway, including GSK-3β and the mammalian target of rapamycin (mTOR), have been reported to act as depression and antidepressants." (PMID 32397675, 2020). "Seven important pathways, such as PI3K-Akt signaling pathway and mTOR signaling pathway, are closely related to the pathology mechanisms of depression." (PMID 32760300, 2020). "Recent studies have suggested that both BDNF and another protein-mammalian target of rapamycin (mTOR) have important roles to play in the development of some mental diseases such as depression and anxiety." (PMID 32198387, 2020). "Clinical studies have also found deficits in the mTOR signaling pathway in subjects with major depressive disorder, and activation of the mTOR pathway is related to antidepressant actions." (PMID 33381149, 2020).
depression (continued). "Protein products of MTOR and TSC2 are implicated via their connections with AKT1 in regulation of synaptic plasticity and memory; these are impaired in depression, possibly as a result of a reduction of hippocampal volumes." (PMID 33193575, 2020). "Seven important pathways, such as PI3K-Akt signaling pathway and mTOR signaling pathway, are closely related to the pathogenesis molecular mechanisms of depression and require further investigation." (PMID 32760300, 2020). "Among cellular pathways affected in the pathophysiology of depression, we can name the mammalian target of rapamycin (mTOR), mitogen-activated protein kinases (MAPK) or glycogen synthase kinase 3 (GSK-3), as discussed." (PMID 32456135, 2020). "The characterization of the mTOR signaling pathway in depression and its action in response to antidepressants show great potential for the identification of new therapeutic targets for the development of antidepressant drugs." (PMID 30828345, 2019). "In vitro histidine was identified as a key regulator of the mammalian target of rapamycin (mTOR) signaling pathway, which has been implicated in the pathogenesis of ASD as well as psychiatric disorders such as bipolar disorder and depression." (PMID 31141890, 2019). "Fluoxetine, the clinical commonly classic antidepressant medication, also has been proved to regulate mTOR signaling in a region-dependent manner in depression-like mice and mainly in the hippocampus." (PMID 30828345, 2019). "Taken together, these findings suggest that pretreatment with the mTOR inhibitor rapamycin significantly blocked the effect of HT8 on the depression- and anxiety-like behaviors." (PMID 30089868, 2018). "It has been elucidated that phosphorylation of the mTOR signaling pathway is severely decreased in patients with major depression, while ketamine, an N-methyl-d-aspartate (NMDA) antagonist, has been shown to increase mTOR activity and relieve depression." (PMID 30200269, 2018). "The mTOR signaling pathway is also related to change synaptic plasticity in stress and depression, and synaptic plasticity is basic for the adaptability of the mammalian brain." (PMID 29558483, 2018). "For example, instant activation of the mammalian target of rapamycin (mTOR) and related signaling pathway is required for the action of KET, whereas the deficiency in this pathway was implicated in depression-like conditions in various chronic animal models." (PMID 30687098, 2018). "mTOR signaling is affected in patients with major depressive disorder as well as animal models of depression and anxiety." (PMID 30532767, 2018). "Bioinformatic analysis revealed that let-7b and let-7c regulates the expression of 27 genes in the PI3k-Akt-mTOR signaling pathway, which has previously been reported to be dysfunctional in depression." (PMID 27483380, 2016). "In contrast, inhibition of mTor by rapamycin reverses the antidepressant effects of ketamine in patients with major depression." (PMID 27490818, 2016). "Findings from our group and others warrant further studies on the mechanism by which parturition and prepregnancy stress alter mTOR and other signaling governing depression." (PMID 27756905, 2016). "For this reason, the contribution of mTOR signaling to synaptic protein synthesis is currently a major research focus for depression." (PMID 26522512, 2015). "A postmortem study also showed considerable deficits in mTOR signaling in the prefrontal cortex of subjects diagnosed with major depressive disorder." (PMID 26150775, 2015). "VGF (nonacryonimic) and phosphatidylinositol 3-kinase (PI3K)/AKT (also known as protein kinase B, PKB)/mammalian target of rapamycin (mTOR) signaling play pivotal roles in depression." (PMID 25542689, 2014). "Thus, targeting the AKT/mTOR pathway is essential for developing effective interventions for depression, and the potential regulatory role of Bifidobacterium breve BB05 in this complex network deserves further exploration." (PMID 39949541, 2025).
depression (continued). "Furthermore, recent researches found that the mTOR/BDNF pathway in prefrontal cortex and hippocampus of mice is disrupted in depression and linked to impaired behavioral functions." (PMID 41234534, 2025). "Additionally, while the research emphasized the AKT/mTOR signaling pathway, depression involves complex and diverse pathological mechanisms, warranting exploration of other potential pathways." (PMID 39949541, 2025). "Additionally, the crosstalk between 5-HT1 AR and β-catenin alters neuronal excitability through Erk, 5-HT, and mTOR signaling, providing protective effects against depression while potentially exacerbating anxiety." (PMID 40266546, 2025). "For example, activating autophagy by modulating the mTOR pathway or using natural products may provide new strategies for the treatment of depression." (PMID 40497971, 2025). "Some studies also have detected that DBS and certain antidepressants that alleviate depression-like behavior may act through the mTOR signaling pathway." (PMID 41234534, 2025). "Thus, our findings provide insight into the key therapeutic effect of COS and novel molecular mechanism of microglial Akt/mTOR/NF-κB/IL-1β signaling pathway for the treatment of major depression." (PMID 40011631, 2025). "Additionally, MOO has been shown to activate PI3K/Akt/mTOR-mediated mitophagy to reduce neuroinflammation and mitochondrial damage during hypertension-induced depression." (PMID 40362100, 2025). "Possible mechanisms linking regular physical exercise and MVPA to reduce the anxiety and depression include the elicitation of endorphins, the initiation of thermogenesis, the activation of the mTOR axis in certain brain regions, and the discharge of neurotransmitters like dopamine and serotonin." (PMID 38390250, 2024). "Our results further demonstrate that SHD might regulate the microbiota-derived tryptophan metabolism to trigger the AMPK/mTOR pathway of autophagy, enhancing the intestinal barrier, which can exert a therapeutic effect on depression-like behaviors." (PMID 39351096, 2024). "The results indicate that SHD could regulate microbiota-derived tryptophan metabolism and AMPK/mTOR pathway, and enhance the intestinal barrier function to ameliorate depression-like behaviors." (PMID 39351096, 2024). "The downstream of PI3K/AKT pathway includes caspase 9 (CASP9), glycogen synthase kinase 3 (GSK3), protein 21 (P21), mammalian target of rapamycin (mTOR), and other pathways, which have been widely reported to play a regulatory role in inflammatory response, depression, and cancer development." (PMID 39723076, 2024). "In conclusion, SHD could regulate microbiota-derived tryptophan metabolism, and trigger the AMPK/mTOR pathway of autophagy, enhancing the intestinal barrier function to improve depression-like behaviors in the CUS model." (PMID 39351096, 2024). "In addition, mTOR signaling is involved in the antidepressant effects of some clinical antidepressants used as the first choice for treating patients with depression, including ketamine, escitalopram, paroxetine, and tranylcypromine." (PMID 38365306, 2024). "Interestingly, several recentre ports have related the Focal Adhesion -PI3K-Akt-mTOR-signaling pathway, the one predicted by String analysis of the candidate proteins, with the pathogenesis of depression." (PMID 39146369, 2024). "Moreover, the PI3K-Akt signaling pathway can also modulate the activity of other cellular pathways related to depression and addiction, such as the mammalian target of rapamycin (mTOR) signaling pathway." (PMID 38926475, 2024). "Furthermore, dysregulation of expression in mTOR signaling pathways, which modulate autophagy, has been found in victims of depression." (PMID 39351096, 2024). "Interestingly, blocking mTOR signaling completely prevents ketamine from inducing synaptogenesis and its antidepressant-like behaviors in depression models, highlighting the pivotal role of mTOR’s in ketamine’s rapid antidepressant effects." (PMID 39769420, 2024).
depression (continued). "Importantly, the mTOR/Wnt/β-catenin signaling/pathway and mitochondrial energetics are mechanisms to further investigate in the spectrum of depression improvement from response to emergent mania aligning with the available genetic data." (PMID 38351009, 2024). "This study tested the hypothesis that rosiglitazone (RGZ) has an antidepressant impact on dexamethasone (DEXA)-induced depression by analyzing the function of the pAKT/p38MAPK/mTOR pathway and NGF through regulation of AMPK." (PMID 36979839, 2023). "This suggests that improvement of lipid metabolism or enhancement of autophagy via the AMPK/mTOR pathway may be a potential candidate target for the therapy of obesity and depression." (PMID 37387537, 2023). "Furthermore, abnormal expression of AKT1 and mTOR signaling pathways, which regulate autophagy, has been found in patients with depression." (PMID 38026940, 2023). "Duman’s group were the first to discover that mTOR activation in brain is required for the rapid antidepressant mechanism of ketamine; soon after that, mTOR became a major target in the studies of depression and antidepressant action." (PMID 34983570, 2022). "In conclusion, MMXY may be effective in improving retinal morphology and function as well as anxiety and depression-like behaviors in CUMS rats by regulating the PI3K/Akt/mTOR pathway." (PMID 36278192, 2022). "There is a lack of the investigation to demonstrate whether SGKL can target PI3K/Akt/mTOR pathway based on altered gut microbiota, leading to the improvement of depression progression." (PMID 35713215, 2022). "How dose PI3K/Akt/mTOR pathway effect on depression progression via activated microglia?" (PMID 35713215, 2022). "Intracerebroventricular (ICV) injection of alarin has also been proven to improve depression-like behaviors through the alarin-mediated restoration of UCMS-induced reduction of phospho-mTOR and phospho-4E-BP1 in the prefrontal cortex, hippocampus, hypothalamus, and olfactory bulb." (PMID 36506414, 2022). "Importantly, SGKL treatment targets the PI3K/Akt/mTOR pathway in improving depression‐like behaviour, microglia activation, and inflammation." (PMID 35713215, 2022). "In addition, as evidence suggesting that echinacoside can upregulate brain Akt and ERK signaling, their downstream mTOR signaling is suggested as a convergent mechanism of fast-acting antidepressant effects and closely related to depression pathophysiology." (PMID 34983570, 2022). "Importantly, SGKL treatment targets the PI3K/Akt/mTOR pathway in improving depression‐like behavior, microglial activation, and inflammation." (PMID 35713215, 2022). "Our results confirmed that the antidepressant-like effects of rapastinel in stress and depression may correlate with ERK/mTOR signaling." (PMID 36550125, 2022). "We showed a novel mechanism of gut microbiota in causing depression; gut microbiota cause changes in phosphorylation of the PI3K/Akt/mTOR pathway, which mediates microglial activation and subsequent inflammation, eventually causing the development of depression." (PMID 35713215, 2022). "The prefrontal cortical FKBP5 induction may be used as an mTOR-independent antidepressant to prevent depression." (PMID 35222638, 2022). "Our previous study determined SGKL might contribute to alleviating depression symptoms through the PI3K/Akt/mTOR pathway." (PMID 35713215, 2022). "The activation of the AKT/mTOR cascade enhances the synaptic proteins synthesis followed by an increase in the number and function of synapses that contributes to the rapid elimination of depression symptoms." (PMID 35337082, 2022). "Given the therapeutic importance and potential for optimizing pharmaco therapies against depression, research labs at AbbVie, Servier, Pfizer, and Alkermes revisited the question of whether ketamine activates mTOR using PFC synaptosomes." (PMID 35465614, 2022).